E2F2 (E2F transcription factor 2)
Diseases named in the same sentence as E2F2 in open-access papers (continued):
Sharing a sentence is not in itself a finding about the gene and the disease.
glioma (24 papers, 2017 to 2025). A benign or malignant brain and spinal cord tumor that arises from glial cells (astrocytes, oligodendrocytes, ependymal cells). "E2F8 and E2F2 have been also implicated in the maintenance of glioma stem cell phenotypes and cell transformation." (PMID 33804958, 2021). "E2F2 has been linked to the maintenance of glioma stem cell phenotypes and cell transformation." (PMID 32488114, 2020). "Treatment with let-7b decreases proliferation of glioma cells by binding to E2F2 mRNA 3′ UTR to decrease E2F2 expression." (PMID 37370851, 2023). "The latest study has elucidated that E2F2 drives glioma’s progression via the PI3K/Akt pathway in a 6-phosphofructo-2-kinase/fructose-2,6-biphosphatase 4 (PFKFB4)-dependent manner." (PMID 35353027, 2022). "It has been discovered that E2F2, a direct target gene of Let-7b, can be used for targeted treatment to promote the proliferation and stem-like cell of glioma cells." (PMID 35069909, 2022). "Researchers have demonstrated the overexpression of E2F2 in glioblastoma multiforme and low-grade glioma tissues." (PMID 36551770, 2022). "In glioblastoma multiforme, E2F2, as a direct target gene of Let-7b, is confirmed to promote the proliferation of glioma and glioma stem-like cells." (PMID 35069909, 2022). "Genes associated with the neuronal differentiation pathway (Pcsk9, Runx1, Cebpb, Fzd4, Wnt7a, Ascl1, Fzd2, Edn3, Olig2, and Gpc2), gliomas (Shc1, Cdk4, E2f2, and Ccnd1), and cell cycle (Bub1b, Bub, Ccnb1, Ccnb2, and Cdc20) were significantly downregulated." (PMID 36147849, 2022). "Another study analyzed E2F2 mRNA expression levels in the human brain and central nervous system cancers types via Oncomine and GEPIA databases." (PMID 36551770, 2022). "Analysis of high-grade glioma (HGG) indicated that E2F2 and E2F8 are highly correlated with oncogenes driving proliferation and therapeutic resistance and E2F8 independently predicts poorer survival." (PMID 33804958, 2021). "Downregulation of E2F2 was shown to inhibit glioma cell growth in vitro and in vivo by inducing cell cycle arrest in G0/G1." (PMID 33381564, 2020). "Our results thus suggest that PPARα inhibits human glioma cell proliferation through a miR-214- and E2F2-dependent pathway and identify novel potential molecular targets for the treatment of human gliomas." (PMID 29862267, 2018). "To confirm this, we performed luciferase reporter assays in human glioma cells expressing luciferase driven by WT human E2F2 3′-UTR or a mutant construct in which the miR-214 binding site is deleted." (PMID 29862267, 2018). "Taken S that PPARα inhibition of glioma cell growth is mediated by the sequential effects on miR-214 transcription and E2F2 expression." (PMID 29862267, 2018). "To test further the specificity of IGFBP2, we also analyzed MYC, FOXM1, and E2F2, which have been associated with malignant progression of IDH-mutant glioma." (PMID 27852048, 2017). "miR-125b influences glioma stem cell proliferation by directly targeting E2F2." (PMID 39959433, 2024). "E2F2 expression correlates directly with tumor grade and indirectly with survival in glioma." (PMID 37370851, 2023). "This study reveals the existence of critical molecular crosstalk between TAMs and glioma mediates through the LINC01232/E2F2/NBR1/MHC‐I axis to support malignant tumor growth, indicating that targeting this axis may have therapeutic potential." (PMID 37097629, 2023). "miR-4731-5p/E2F2 axis also regulated the progresses of glioma cells." (PMID 35342398, 2022). "Studies have shown that downregulation of E2F2 inhibits glioma cell growth." (PMID 33381564, 2020). "Having shown that PPARα promotes miR-214 transcription and that miR-214 overexpression reduces E2F2 protein levels in glioma cells, we next asked whether the inhibitory effects of PPARα on proliferation were mediated through miR-214 and E2F2." (PMID 29862267, 2018).
glioma (continued). "Importantly, glioma cell proliferation and E2F2 protein expression were both increased in PPARα-overexpressing cells infected with AS-miR-214 compared with PPARα sequence." (PMID 29862267, 2018). "Here, we found that the proliferation of human glioma cells is inhibited by PPARα overexpression, which promotes transcription of DNMO3os, thereby increasing miR-214 levels and consequently decreasing translation of its target E2F2 mRNA." (PMID 29862267, 2018). "In glioma, TAM‐secreted exosomal LINC01232 binds to E2F Transcription Factor 2 (E2F2), promoting its nuclear translocation and enhancing NBR1 transcription." (PMID 40673641, 2025). "A distinct glioma stem cell population was identified, characterized by high proliferative potential and an enrichment of E2F1, E2F2, E2F7, and BRCA1 regulons, with implications for tumor growth and patient outcomes." (PMID 39981232, 2025). "The LINC01232/E2F2/NBR1/MHC‐I expression levels among normal brain tissues (NBT), low‐grade glioma tissues (LGG), and high‐grade glioma tissues (HGG) were compared." (PMID 37097629, 2023). "Similar results can be found in glioma, osteosarcoma, gastric cancer and melanoma, it’s not surprising that E2F2 is regarded as an oncogene." (PMID 33115417, 2020). "E2F2 was also observed to be upregulated in astrocytomas, and more importantly, it exhibited a distinctive expression in CD133‐positive cells which are considered to be enriched in glioma stem‐like cells." (PMID 28378523, 2017). "We observed that E2F2 and E2F8 mRNA levels are higher in GBM when compared to normal brain and gliomas grade II and III and, similarly to Msi1, their expression levels decrease during neuronal differentiation." (PMID 33804958, 2021).
gastric cancer (19 papers, 2015 to 2026). A primary or metastatic malignant neoplasm involving the stomach. "Enhanced NELFE and E2F2 expression levels were associated with poor survival rates in gastric cancer patients." (PMID 34295816, 2021). "Comparison of E2F2 mRNA expression with miR- 31in gastric cancer exhibited an inverse association (r = 0.122,p = 0.027)." (PMID 27174918, 2016). "In the current study, we found that E2F2 expression was inversely associated with miR-31 levels in gastric cancer tissues." (PMID 27174918, 2016). "We then associated E2F2 expression with clinicopathological characteristics from 40 gastric cancer patients." (PMID 27174918, 2016). "Previous studies and the public database analysis indicate that E2F2 also plays a protective prognostic role in gastric cancer, but E2F2-deficiency in this study weakened the proliferation and migration of gastric cancer cell lines, a result consistent with the findings of previous studies." (PMID 38371373, 2024). "E2F2 has been extensively researched in the past few decades in association with gastric cancer." (PMID 36923953, 2023). "E2F2 expression was upregulated in gastric cancer tissues, and inversely associated with miR-31 levels, while knockdown of E2F2 expression mimicked miR-31 anti-tumor activity in gastric cancer cells, but the ectopic expression of E2F2 rescued the miR-31-mediated inhibition in gastric cell lines." (PMID 27174918, 2016). "Silencing E2F2 had been shown to impair cell growth, invasion, and migration in gastric cancer cells." (PMID 41491570, 2026). "In gastric cancer, reducing the expression level of E2F2 inhibited the proliferation and migration of gastric cancer cells." (PMID 36855119, 2023). "E2F2 overexpression in gastric cancer cells improves migration and invasion by down-regulating PI3K/AKT/mTOR-mediated autophagy." (PMID 36139919, 2022). "E2F2, a member of the E2F transcription factor family, is overexpressed in gastric cancer with poor overall survival." (PMID 36139919, 2022). "The results showed that the higher transcriptional levels of both E2F2 and E2F8 were associated with better overall survival in gastric cancer patients." (PMID 35371973, 2022). "Similar results provided evidence that miR-31 inhibits E2F2 expression to suppress tumor cell malignant phenotypes in gastric cancer." (PMID 35069909, 2022). "Similar to NELFE, the E2F2 protein was ubiquitously expressed in gastric cancer cells, and the expression level was higher in BGC-823 and AGS cells." (PMID 34295816, 2021). "In gastric cancer, E2F2 also acts as an oncogene to inhibit the proliferation and migration of gastric cancer cells by knocking down the expression level of E2F2." (PMID 34295816, 2021). "In BGC-823 and AGS gastric cancer cells, E2F2 knockdown inhibited cell growth and metastasis both in vitro and in vivo." (PMID 34295816, 2021). "E2F2 expression was reported to be upregulated in gastric cancer, which is in accordance with the data of the present study." (PMID 34295816, 2021). "E2F2 was found to be overexpressed in human gastric cancer tissues compared with normal gastric tissues." (PMID 34295816, 2021). "Level of E2F2 mRNA and protein was significantly reduced following the ectopic expression of miR-31 in gastric cancer cells." (PMID 27174918, 2016). "Eventually, E2F2 was identified as a candidate target of miR-31 for further investigation and our previous study also showed altered expression and role of E2F2 in gastric cancer." (PMID 27174918, 2016). "In the current study, we observed that E2F2 was overexpressed in gastric cancer tissues and moreover, high E2F2 levels were positively associated with poor tumor differentiation, lymph node metastasis, advanced T stage and worse overall survival." (PMID 27174918, 2016). "We then assessed E2F2 expression in gastric cancer tissue samples and found that level of E2F2 mRNA was increased in 29 of 40 gastric cancer tissues compared to the adjacent normal tissues." (PMID 27174918, 2016).
gastric cancer (continued). "Mechanistically, miR-31 antitumor activity was through targeting of E2F2 expressionin gastric cancer cells." (PMID 27174918, 2016). "CIBERSORTx analysis of the proportion of tumor-infiltrating immune cells (TICs) revealed that immune cells are correlated with E2F2 expression, suggesting that E2F2 might be responsible for the preservation of the immunodominant status for gastric cancer." (PMID 38807594, 2024). "Therefore, miRNA and E2F2 have broad application prospects and development space in the research field of gastric cancer." (PMID 38807594, 2024). "DNA replication may be associated with E2F2, according to research, which shows that MTA2 impairs DNA replication stress in gastric cancer cells and increases their sensitivity to PARP inhibition." (PMID 36923953, 2023). "Previously, E2F2 has been reported for its role in development of gastric cancer growth." (PMID 36389725, 2022). "Additionally, H19 was demonstrated to promote gastric cancer cells to proliferate and invade through the miR-138/E2F2 axis." (PMID 34295816, 2021). "Furthermore, we used tail vein injection of BGC-823 cells to study the effect of E2F2 on the metastatic ability of gastric cancer cells in vivo." (PMID 34295816, 2021). "In summary, we have demonstrated that NELFE and E2F2 play a vital role in the proliferation and metastasis of gastric cancer, which may be mediated by effects on the tumor microenvironment." (PMID 34295816, 2021). "Therefore, through large number of in vivo and in vitro studies, we confirmed that NELFE facilitated the viability and metastasis of gastric cancer cells specifically by stabilizing the mRNA of E2F2." (PMID 34295816, 2021). "Therefore, E2F2 also promotes the growth and metastasis of human gastric cancer cells in vitro and in vivo." (PMID 34295816, 2021). "NELFE and E2F2 inhibitors could be used as potential therapeutic targets for gastric cancer treatment." (PMID 34295816, 2021). "We examined the protein levels of E2F2 in human gastric cancer cells." (PMID 34295816, 2021). "In addition, mutation of the predicted-binding site of miR- 31 on the E2F2 3′-UTR can rescue the luciferase activity, indicating that E2F2 is a direct target of miR- 31 in gastric cancer cells." (PMID 27174918, 2016). "Moreover, our current results indicated that E2F2 was involved in progression, lymph node metastasis and prognosis of gastric cancer patients." (PMID 27174918, 2016). "Moreover, knockdown of E2F2 in gastric cancer cells produced an anti-proliferative, apoptosis increased, G1 phase retardation and migratory and invasive reduced effect, which was similar to the results when miR-31 upregulation." (PMID 27174918, 2016). "To evaluate whether E2F2 serves as a critical mediator of miR-31 in gastric cancer cells, we suppressed E2F2expression in SGC-7901 and MGC-803 cells using a specific siRNA." (PMID 27174918, 2016). "Moreover, the restoration of E2F2 expression in cells stably expressing miR-31 was able to counteract the inhibitory effects of miR-31 in the gastric cancer cells." (PMID 27174918, 2016). "Moreover, Kaplan-Meier analysis indicated that patients with high E2F2-expressed gastric cancer tended to have worse overall survival than those with low E2F2-expressed tumor (p = 0.047)." (PMID 27174918, 2016). "Therefore, E2F2 is necessary for NELFE to promote human gastric cancer." (PMID 34295816, 2021). "To verify the effect of E2F2 knockdown on progression of gastric cancer, we utilized specific RNAi to transfect it into gastric cancer cells and found that silence E2F2 could remarkably reduce cell proliferation, migration and invasion, but enhanced tumor cells to undergo apoptosis." (PMID 27174918, 2016).
gastric cancer (continued). "Studies have shown that E2F2 regulates autophagy through the PI3K/Akt/mTOR pathway, which in turn affects the migration of gastric cancer cells." (PMID 38668684, 2024). "Cellular experiments confirmed that the transcriptional level of E2F2 and E2F8 affected cell proliferation and migration in gastric cancer cell lines." (PMID 38371373, 2024). "The results demonstrated that E2F1, E2F2 and E2F4 were overregulated in the gastric cancer samples compared with normal samples." (PMID 25646628, 2015). "The qPCR assay results showed the mRNA levels of E2F2 and E2F8 were significantly upregulated in the gastric cancer tissues compared with the corresponding normal tissues, which was consistent with both the transcriptomic database and the findings of previous studies." (PMID 38371373, 2024). "In addition, after analyzing the correlation between NELFE and E2F2, we found that the expression levels of NELFE and E2F2 in gastric cancer tissue were significantly positively correlated." (PMID 34295816, 2021). "The biological role of E2F2 in gastric cancer (GC) also remains unclear." (PMID 34091441, 2021). "Furthermore, miRNAs differentially expressed in gastric cancer were able to regulate expression of E2F1, E2F2, E2F5 and E2F7, indicating that miRNAs-altered expression of E2Fs proteins is important factors in gastric cancer development or progression." (PMID 25646628, 2015). "Furthermore, miRNAs (miR-125a-5p, miR-331–3p, miR-17, miR-150, miR-155, miR-27b, miR-31, miR-92a and miR-509–5p), which differentially expressed in gastric cancer, were found to regulate expression of E2F1, E2F2, E2F5 and E2F7 in this study." (PMID 25646628, 2015). "In gastric cancer, E2F2 has not been systematically studied previously." (PMID 34295816, 2021). "Moreover, CIBERSORTx analysis of the proportion of tumor-infiltrating immune cells (TICs) revealed that immune cells are correlated with NELFE and E2F2 expression, suggesting that NELFE and E2F2 might be responsible for the preservation of the immunodominant status for gastric cancer." (PMID 34295816, 2021).
non-small cell lung carcinoma (14 papers, 2017 to 2025). A group of at least three distinct histological types of lung cancer, including non-small cell squamous cell carcinoma, adenocarcinoma, and large cell carcinoma. "The higher E2F2 expression levels were significantly associated with poor prognosis in patients with non-small-cell lung cancer." (PMID 37047293, 2023). "The genes included the pathway non-small cell lung cancer were E2F2, E2F3, TGFA, PRKCG, CDK6, EGF, and CDK4, which were all expressed at significantly higher levels in LUSC tissues in comparison to that in the non-cancer group." (PMID 29394946, 2018). "E2F2 knockdown suppresses cell viability and colony formation in non-small cell lung cancer." (PMID 34944699, 2021). "Another report has also demonstrated that miR-936 could directly target E2F2 to inhibit the invasion and proliferation of non-small cell lung cancer cell." (PMID 32117723, 2020). "For example, B-MYB accelerates the cell cycle in colorectal cancer cells 47 by upregulating the E2F2/ERK/AKT signaling pathway, and suppressing IGFBP3 expression to promote proliferation and metastasis in non-small cell lung cancer." (PMID 40303285, 2025). "For example, circPVT1 contributes to non-small cell lung cancer (NSCLC) cell growth and migration by inhibiting miR-125b to activate E2F2 expression." (PMID 30922402, 2019). "E2F1, E2F2, and E2F3 are up-regulated in non-small cell lung cancer." (PMID 29254182, 2017).